GDF9 (growth differentiation factor 9)
Description:
Required for ovarian folliculogenesis. Promotes primordial follicle development. Stimulates granulosa cell proliferation. Promotes cell transition from G0/G1 to S and G2/M phases, through an increase of CCND1 and CCNE1 expression, and RB1 phosphorylation. It regulates STAR expression and cAMP-dependent progesterone release in granulosa and thecal cells. Attenuates the suppressive effects of activin A on STAR expression and progesterone production by increasing the expression of inhibin B. It suppresses FST and FSTL3 production in granulosa-lutein cells.
Synonyms: POF14
Tractability: Antibody: UniProt places it where antibodies can reach, with medium confidence; UniProt predicts a signal peptide or a membrane-spanning region; its Gene Ontology location is reachable by antibodies, with medium confidence.
Gene: Protein-coding gene on chromosome 5 (132,861,181 to 132,866,884, reverse strand). Ensembl gene ENSG00000164404.
Subcellular location: Secreted
Subcellular location (Human Protein Atlas): Golgi apparatus; Cytosol; Predicted to be secreted
Gene Ontology:
Molecular function: cytokine activity; growth factor activity
Biological process: positive regulation of cell population proliferation; regulation of progesterone secretion; cell surface receptor protein serine/threonine kinase signaling pathway; female gamete generation; transforming growth factor beta receptor signaling pathway
Cellular component: cytoplasm; extracellular region
Genetic constraint (gnomAD): Loss-of-function variants: 23 observed, 28.83 expected, observed/expected ratio (o/e) 0.8, 90% interval 0.57 to 1.13. The upper end of that interval is the gene's LOEUF score, 1.13, which puts it in group 4 of 6, group 1 being the genes least tolerant of losing a copy. Missense variants: 451 observed, 460.37 expected, observed/expected ratio (o/e) 0.98, 90% interval 0.91 to 1.06. Synonymous variants: 160 observed, 170.03 expected, observed/expected ratio (o/e) 0.94, 90% interval 0.83 to 1.07.
Homologues: Orthologues: chimpanzee GDF9 (99% identical), macaque GDF9 (94% identical), pig GDF9 (75% identical), rat Gdf9 (72% identical), mouse Gdf9 (71% identical), rabbit GDF9 (71% identical), dog GDF9 (66% identical), guinea pig GDF9 (55% identical), tropical clawed frog gdf9 (45% identical), zebrafish gdf9 (37% identical). Paralogues in human: BMP15 (26% identical), BMP4 (16% identical), INHBA (16% identical), BMP10 (16% identical), BMP3 (16% identical), GDF6 (16% identical), INHBB (16% identical), INHBE (16% identical), GDF2 (15% identical), GDF7 (15% identical), BMP6 (15% identical), BMP2 (14% identical), and 19 more.
Diseases named in the same sentence as GDF9 in open-access papers:
GDF9 is named in the same sentence as 53 diseases in open-access papers, as found by Europe PMC text mining. Sharing a sentence is not in itself a finding about the gene and the disease. The quoted sentences say what the papers report.
Infertility (45 papers, 2006 to 2025). "The GDF9 S395F and S427R mutant variants enhance the ovulation rate in heterozygotes, however, the homozygous form results in infertility." (PMID 40699678, 2025). "In sheep, homozygous inactivating mutations in the genes encoding BMP15 and GDF9 have been identified as being associated with infertility." (PMID 36650852, 2023). "GDF9 plays a pivotal role during early folliculogenesis, and deletion of GDF9 in mice causes follicular arrest at the primary stage and infertility." (PMID 33739800, 2021). "Mutations in GDF9 have different effects on ovulation rate and can even cause infertility in some cases." (PMID 33642793, 2021). "In this study, the relationship of three variables was also examined using regression analysis and revealed a significant association among TNFα, GDF-9, and KitL expression cultured in PF from infertile women with endometriosis added with curcumin (p< 0.05)." (PMID 31417983, 2018). "Since the follicles in Rps26fl/fl/Gdf9-Cre ovary were mostly arrested at the pre-antral follicle stage, thus the small size of the ovary and the infertility are associated with the failure to undergo the NSN to SN transition." (PMID 30451825, 2018). "Study in GDF-9 deficient female mice has resulted in impaired follicular development after primary follicle growth that causes infertility." (PMID 31417983, 2018). "The BMP15 fecundity alleles show an X-linked overdominance inheritance pattern with infertility in homozygous females, while the GDF9 fecundity alleles have an autosomal overdominance inheritance pattern with infertility in homozygous females." (PMID 17205129, 2006). "Notably, GDF9 395 S>F and 427 S>R in sheep lead to an increase in ovulation rate due to heterozygous mutations, whereas homozygous mutations lead to infertility, which is of great significance for molecular-level animal breeding." (PMID 39057020, 2024). "The Exosc10cKO(Gdf9) mouse model shows greater penetrance of the phenotype since it causes severe infertility, which could be explained by earlier inactivation of Exosc10 by the Cre recombinase during oogenesis." (PMID 36923944, 2023). "BMPR2 activation influences granulosa cell proliferation, BMP15 and GDF9 signaling, and disruptions in this pathway can lead to infertility and reproductive abnormalities." (PMID 38275408, 2024). "Mutations in the GDF9 gene have been reported to cause POI and infertility among women from different ethnic groups." (PMID 38672141, 2024). "In F2 females from the 68.5 mg/kg treatment group, the Gdf-9 levels were significantly reduced, likely indicating infertility, which is in line with previous research." (PMID 39765742, 2024). "On the other hand, infertile patients with endometriosis were found to have unchanged GDF9 gene expression levels in cumulus cells of antral follicles compared to controls." (PMID 36380138, 2023). "REC8- and SMC1β-null mutations are sterile because of meiotic failure, whereas Smc1βfl/fl;Gdf9-iCre female mice are fertile, in contrast to the infertility observed in our breeding trials." (PMID 34935904, 2021). "Deletion of Gdf9 results in arrest of folliculogenesis at the primary follicle stage and complete infertility in female mice because the cuboidal granulosa cells fail to proliferate." (PMID 29641448, 2018). "The mean expression of GDF-9 in bovine COC cultured in PF from infertile women with endometriosis+curcumin (2.67 ± 0.98) increased compared to those cultured without curcumin (0.50 ± 0.67) but reduced compared to the control (5.83 ± 1.58)." (PMID 31417983, 2018). "In accordance with infertility in furfl/fl;Zp3-Cre mice, the furfl/fl;Gdf9-Cre female mice were also infertile." (PMID 28569793, 2017). "Blood genomic DNA was extracted from a subset of low-ovulating, prolific and infertile ewes of the “W” flock, and the entire coding sequences of GDF9 and BMP15 were sequenced." (PMID 28506298, 2017).
Infertility (continued). "Inactivatingmutations of either or both GDF9 andBMP15 lead to infertility in homozygous ewes, butincreased fertility in heterozygous ewes." (PMID 25210607, 2012). "Additionally, pigs have been used to explore the role of growth differentiation factor 9 (GDF9) in ovarian function, and insights into this molecular mechanism have informed infertility research strategies." (PMID 41479424, 2025). "The depletion of Dcaf2 with Stra8‐Cre did not affect ovulation in female mice but caused infertility (data not shown), consistent with the results in which Dcaf2 was depleted with Gdf9‐Cre." (PMID 38837535, 2024). "GDF9 is responsible for GC proliferation and differentiation to CCs; its levels continuously rise during folliculogenesis until ovulation and absence of GDF9 leads to arrest at the primary follicular stage with subsequent follicular atresia and infertile mice." (PMID 36397149, 2022). "An increased understanding of BMP15/GDF9 signaling during human oocyte maturation may improve the clinical treatment for women with ovulation dysfunction and infertility, especially in connection with in vitro maturation (IVM)." (PMID 35986324, 2022). "GDF9 null mice are infertile due to severe follicle and oocyte abnormalities." (PMID 32046451, 2020). "Cxxc1fl/fl;Gdf9-Cre female mice (hereafter referred to as Cxxc1oo–/–) are completely infertile." (PMID 30154440, 2018). "In conclusion, our study suggests that the reduction of GDF9 and BMP15 expression starting from the primary follicle stage can cause follicular development disorders and insufficient oocyte maturation that can further lead to subfertility or infertility." (PMID 28903889, 2018). "Several different types of mutations and polymorphisms in GDF9 have been reported to cause significant negative effects inducing infertility, ovulation impairment, and susceptibility to premature ovarian failure in some mammalian species." (PMID 30327782, 2018). "The objective of our study was to evaluate whether curcumin could improve growth factors expression in bovine cumulus-oocyte complexes (COC)s by analyzing GDF-9, KitL, and TNFα expressions in culture medium with PF from infertile women with endometriosis." (PMID 31417983, 2018). "No streak ovaries, which are considered indicators of infertility due to homozygocity forsome mutations in GDF9 and BMP15, were found." (PMID 25210607, 2012). "Both studies have provided essential information on the expression of GDF-9 and BMP-15 in infertile couples undergoing IVF and the promising clinical use of the OSF as non-invasive markers to predict oocyte competence." (PMID 34527670, 2021). "In this study, GDF-9 and KitL expressions in bovine COC cultured with PF from infertile women with endometriosis were significantly reduced compared to control." (PMID 31417983, 2018). "Female mice lacking GDF-9 can still form primordial and primary follicles, but it affects their follicle development, resulting in infertility." (PMID 38254930, 2023). "Infertility was observed in mice when the GDF9 gene was neutralized and follicular development did not progress from the primary follicle stage, in addition to decreasing granulosa cell proliferation." (PMID 36650852, 2023). "Female mice lacking the GDF9 gene can still form primordial follicles, but the oocytes stop growing when they reach the primary follicle stage, leading to complete infertility." (PMID 36499673, 2022). "GDF9 null mice ovarian follicles do not progress beyond the primary follicle stage, which results in infertility." (PMID 32046451, 2020). "In this study, the addition of curcumin to the culture medium of PF from infertile women with endometriosis resulted in more improved GDF-9 expression than those without curcumin." (PMID 31417983, 2018). "A lack of GDF9 can impair follicle growth, potentially leading to infertility." (PMID 40842627, 2025).
Infertility (continued). "When mice are experimentally rendered infertile by cyclophosphamide, treatment with conditioned medium and PRP was able to boost expression of ‘mothers against decapentaplegic’ homologs 1 and 2 (SMAD1, SMAD2), growth differentiation factor-9 (GDF9), and bone morphogenetic protein-15 (BMP15)." (PMID 37505061, 2023). "GDF9 gene has shown to play an essential role in folliculogenesis and granulosa cells proliferation in chickens, which leads to improved follicle development and that a lack of GDF9 expression might affect the follicle growth and lead to infertility." (PMID 35059524, 2022). "Furthermore, the total number of follicles was comparable in adult Smc3fl/fl, Smc3fl/fl;Gdf9-iCre and Smc3fl/fl;Zp3-Cre female mice, suggesting that differences in ovarian reserve do not account for infertility." (PMID 34935904, 2021). "This infertility phenotype may be due to disruption of the PCSK (proprotein convertase subtilisin kexin) cleavage site of the GDF9 proprotein, preventing the conversion of GDF9 to dimeric, mature GDF9, which is the biologically active form of the protein." (PMID 33671790, 2021). "Although effects of FecGH and FecGT variants have never been tested in vitro, it is strongly thought that GDF9 loss-of-function mutations might alter both GDF9 homodimer and BMP15/GDF9 heterodimer pathways leading to infertile animals." (PMID 23637641, 2013). "In cattle, GDF9 and BMP15 play indispensable roles in follicular development and the ovulatory process, while in humans, mutations or deficiencies in these factors are more often associated with diminished ovarian reserve or subfertility rather than absolute infertility." (PMID 41462676, 2025). "In GDF9-null mice, folliculogenesis does not progress beyond the primary stage, while BMP15-null mice have impaired oocyte maturation that leads to infertility." (PMID 29047400, 2017). "In the GDF9 null mice folliculogenesis does not progress beyond the primary stage, while BMP15 null mice had impaired oocyte maturation leading to infertility." (PMID 25543533, 2014). "Similarly, a study that involved 196 infertile couples undergoing IVF, revealed that the COCs of women who achieved pregnancy expressed higher GDF-9 and BMP-15 mRNA concentrations than those who did not achieve pregnancy." (PMID 34527670, 2021).
premature ovarian failure (13 papers, 2013 to 2025). "The identification of GDF9 missense and nonsense mutations in premature ovarian failure (POF) patients but also in mothers of dizygotic twins suggests that altered GDF9 function is involved in ovarian dysfunction and polyovulatory phenotypes." (PMID 23637641, 2013). "Similarly, studies have shown that early follicle development in rat ovaries irradiated during the neonatal period results in oocytes that strongly express GDF9, which is linked to premature ovarian failure." (PMID 39765742, 2024). "In human genetic studies, GDF9 and BMP15 variants are found in women with premature ovarian failure and amenorrhea, suggesting that GDF9 and BMP15 could be potential PCSK6 substrates in the ovary." (PMID 36362216, 2022). "Pabpn1fl/fl;Gdf9-Cre knockout female mice were infertile and had severe primary ovarian insufficiency (POI)." (PMID 36306357, 2022). "Hematoxylin and eosin (H&E) staining showed that the Pabpn1fl/fl;Gdf9-Cre female mice underwent premature ovarian failure as early as at 6 to 8 weeks of age, characterized by oocyte depletion in the ovaries." (PMID 36306357, 2022). "The large number of mutations in the GDF9 and BMP15 genes have been identified in women with premature ovarian failure and in mothers of dizygotic twin." (PMID 36139716, 2022). "In support of this, we found that all follicles including primordial and activated follicles were significantly reduced in Lkb1fl/fl;Gdf9-Cre mice by 6 months of age (and D'), which is termed premature ovarian failure (POF)." (PMID 26745759, 2016). "GDF9 and BMP15 are associated with premature ovarian failure." (PMID 37108426, 2023). "Decreased levels of GDF9 expression could affect ovarian and follicular development and lead to premature ovarian failure." (PMID 36360303, 2022). "In recent years, several studies have investigated the pathological processes of primary ovarian insufficiency (POI) concerning two members of the TGF-β superfamily, BMP15 and GDF9." (PMID 40969411, 2025). "Among the downregulated transcripts and proteins, premature ovarian failure (POF) markers such as Rps26, Figla, Gdf9, Aire and Fmrp1 were detected, so the absence of CDK12 clearly resembles a POF phenotype." (PMID 40148269, 2025).
polycystic ovary syndrome (11 papers, 2016 to 2025). A disorder that manifests as multiple cysts on the ovaries. "It is also known that abnormal GDF9 expression is associated with polycystic ovary syndrome, while mutations of both GDF9 and BMP15 are associated with ovarian failure." (PMID 35209923, 2022). "Alterations of BMP15 and GDF9 were also searched in association with polycystic ovary syndrome (PCOS)." (PMID 32636872, 2020). "While androgens enhance preantral follicle growth by stimulating the GDF924, 25, chronic androgenic stimulation induces antral follicle growth arrest and polycystic ovarian syndrome phenotypes in the rats by GDF9 down-regulation." (PMID 28860512, 2017). "Some studies show no significant androgen effect on AMH, while others suggest a potential influence in conditions like polycystic ovary syndrome (PCOS) BMPs stimulate AMH and AMHR2 expression, with BMP15, often with GDF9, enhancing AMH expression." (PMID 40410629, 2025). "In human cases, several heterozygous variants in GDF9 have been reported to be associated with primary ovarian insufficiency (POI), polycystic ovary syndrome (PCOS), and dizygotic twinning respectively, and one homozygous variant was reported to be associated with POI." (PMID 38643161, 2024).
female infertility (9 papers, 2015 to 2025). Diminished or absent ability of a female to achieve conception. "The oocyte-specific ablation of Lonp using Gdf9-cre or Zp3-cre results in female infertility due to impaired follicle development, loss of the ovarian reserve, and progressive oocyte death (." (PMID 40558552, 2025). "Our recent work on gdf9 in zebrafish showed that the loss of gdf9 gene caused a complete arrest of follicle development at PG stage, leading to failed puberty onset and therefore female infertility, similar to that in mice." (PMID 37713421, 2023). "Whereas Bmp15 null females are subfertile, the additional deletion of a single Gdf9 allele (i.e., Bmp15-/-/Gdf9+/-; hereafter double-mutant, DM) results in female infertility at least in part due to the defective development of cumulus cells." (PMID 36424497, 2022). "The conditional ablation of Furin using Gdf9-cre or Zp3-cre leads to female infertility due to arrested folliculogenesis at the secondary follicle stage." (PMID 40558552, 2025). "The knockout of GDF9 in mice arrested folliculogenesis at primary follicle stage, resulting in female infertility." (PMID 37713421, 2023). "Conditional ablation of Furin by Gdf9-cre or Zp3-cre; Furinfl/fl result in female infertility because of the arrested oogenesis at early secondary follicles." (PMID 35600599, 2022). "Oocyte-specific Lonp ablation by Gdf9-cre or Zp3-cre; Lonp1fl/fl results in female infertility because of impaired follicular development, progressive oocyte death, ovarian reserve loss." (PMID 35600599, 2022). "Based on female infertility with both Gdf9-iCre and Zp3-Cre drivers and by scoring the number of follicles in ovaries, we investigated whether loss of Smc3 impacts ovarian reserve." (PMID 34935904, 2021). "In addition, GDF9 has the potential to improve female infertility." (PMID 36360303, 2022).
ovarian failure (7 papers, 2015 to 2025). "In sheep, GDF9 natural mutations resulted in higher ovulation rate and twin or triplet births in heterozygotes, while in homozygotes a complete primary ovarian failure leading to complete sterility was also reported." (PMID 35893038, 2022). "The c.546G>A (p.Glu182Glu) mutation occurs at exon 2 of the GDF9 gene, which was initially identified in Indian females with ovarian failure." (PMID 25954833, 2015). "In heterozygotes, there are high ovulation rates in GDF9 and BMP15 mutants while the homozygous mutants show a primary ovarian failure, causing complete sterility." (PMID 37239462, 2023). "In sheep, it has been shown that homozygous mutants of GDF9 and BMP15 cause ovarian failure, which leads to sterility." (PMID 37239462, 2023). "This study aimed to determine the role of HSP70 and caspase-3 as apoptotic indicators, as well as VEGF-1 and GDF-9 as viability and differentiation markers, respectively, in MSCs cultivated under low O2 tension for malnutrition-induced ovarian failure in female rats." (PMID 38644927, 2023). "In a previous study, altered expression of Nobox and Gdf9 induced ovarian dysfunction." (PMID 35257353, 2022).